TNF (tumor necrosis factor)
Diseases named in the same sentence as TNF in open-access papers (continued):
Sharing a sentence is not in itself a finding about the gene and the disease.
steatosis (continued). "In this context, it is intriguing that fasting mice develop an intermittent steatosis with increased FFA and have strongly elevated serum TNF concentrations." (PMID 33050035, 2020). "Analyses were conducted on the following outcomes: steatosis, ballooning hepatocytes, NAS-index, fibrosis, IL-8, MCP-1, TNF-α, α-sma, Col1a1, TGF-β, CYP7A1, HC and HT." (PMID 32882802, 2020). "This regulation induces the production of various pro-inflammatory cytokines, such as TNF-α, interferon gamma (IFN-γ), and IL-1β, which are critically regulated hepatic inflammation, steatosis, fibrosis, and HCC." (PMID 32143357, 2020). "Lactobacillus plantarum AR113 and Lactobacillus casei pWQH01 with high bile salt hydrolase active can improve steatosis by reducing the expression of SREBP-1c, ACC, FAS and TNF-α and increasing the expression of AMPK and PPARα in vitro." (PMID 33281535, 2020). "In the present study, with the reduction in the TNF-α and IL-1β expression, much fewer Mac-2- and α-SMA-positive cells were observed in the livers of AG mice with simple steatosis than in NG mice showing progression to NASH." (PMID 31835339, 2019). "Sequential exposure of hepatocytes to high concentrations of fatty acids (FAs) and TNFα resulted in fat overload and oxidative stress, which mimic in vitro the progression of NAFLD from simple steatosis (SS) to steatohepatitis (SH)." (PMID 28971098, 2017). "B. longum with FOS reduces TNF-α, CRP, serum AST levels, HOMA-IR, serum endotoxin, steatosis, and the non-alcoholic steatohepatitis activity index significantly." (PMID 29276488, 2017). "Accumulated evidence has demonstrated that oxidative stress, abnormal cytokine production, especially tumor necrosis factor (TNF), and steatosis play important etiological roles in the pathogenesis of alcoholic liver disease." (PMID 27298813, 2016). "By contrast in mice fed EtOH+Chol, ALT increased to ~270 U/L, steatosis was more extensive and mostly macrovesicular, and expression of proinflammatory molecules (HMGB-1, TLR4, TNFα, ICAM-1) and leukocyte infiltration increased substantially." (PMID 27676640, 2016). "In liver samples, CD4+ T cells, Kupffer cells and monocytes were characterized near hepatocellular necrosis and steatosis in the presence of pro-inflammatory cytokines, IFN-γ and TNF-α." (PMID 28006034, 2016). "In particular, expression of the cytokine tumor necrosis factor-α (TNF-α) is correlated with the severity of steatohepatitis, and reduction of TNF-α with metformin improves steatosis in ob/ob mice." (PMID 26090409, 2015). "The elevated MCP-1 expression level in adipose tissue and increased TNF-α, PEPCK and G6P levels in liver verified the high glyceroneogenesis and hepatic steatosis state in aged MTMR14 KO mice in our study." (PMID 26697164, 2015). "The activation of the innate immune system has an important function in the transition process from steatosis to NAFLD, which includes a number of inflammatory factors, such as TNF-α." (PMID 24396406, 2014). "In humans, serum levels of TNF-α are significantly higher in patients with simple steatosis and NASH than in normal subjects, and TNF-α levels correlate with the stage of fibrosis and with the NAFLD activity score (NAS) in NASH." (PMID 25937854, 2014). "Experimental group: decrease in TNF-α, CRP, AST, HOMA-IR, endotoxin levels; steatosis; NASH activity index." (PMID 25479248, 2014). "The decoction is capable of reducing tumor necrosis factor-α (TNF-α) expression through cathepsin B and the nuclear factor κB pathway in rats with nonalcoholic steatohepatitis and in steatosis HepG2 cells." (PMID 23573117, 2013). "The expression of TNF-a and TNF-a type 1 receptors in patients with steatohepatitis is greater than for those with steatosis alone." (PMID 24188280, 2013).
steatosis (continued). "HFD significantly increased total fat and triacylglyceride contents with macrovesicular steatosis, concomitantly with higher fasting serum glucose and insulin levels, HOMA, and serum TNF-α, IL-1β, and IL-6." (PMID 23082120, 2012). "TNF-α and MDA levels were significantly increased in the steatosis group (TNF-α; 33.4 ± 5.2 vs 26.24 ± 3.47 pg/ml and MDA; 9.08 ± 0.8 vs 3.17 ± 1.45 μM respectively, P < 0.05)." (PMID 18782455, 2008). "Infliximab (anti-TNF-α) reverses the steatosis and the expression of the proinflammatory markers (TNF-α, IL6, IL-1B) and improves insulin signal trasduction in a model of steatosis in rats." (PMID 18782455, 2008). "One-way ANOVA showed that serum IL-10 was 4-fold less in severe steatosis than in mild steatosis (p = 0.038), whereas TNF-α levels increased twice in severe steatosis compared to no steatosis (p = 0.029)." (PMID 42195075, 2026). "Finally, in HFD-fed mice, OLE lowered the LPS, TNF-α, and IFN-γ in the serum, and downregulated the intestinal and liver TLR4+ macrophages, reducing liver inflammation and steatosis." (PMID 40732959, 2025). "Furthermore, HT downregulated the TNF-α and IL-6 mRNA and COX-2 expression in the liver of young male rats exposed to HFD, decreasing both steatosis and inflammation." (PMID 40732959, 2025). "Whereas other steatosis-promoting inflammatory cytokines, such as TNF-α and IFN-γ, are also increased in mice lacking IL-10, their effect is masked by IL-6/STAT3 anti-lipogenic properties." (PMID 41514930, 2025). "In binary logistic regression analysis, the biologics (group), disease activity, disease duration, age, adiponectin, TNF, leptin, PIIINP, and TIMP-1 were sequentially entered as potential confounders, with the dependent variable being the presence of steatosis, based on the Hamaguchi score." (PMID 39598344, 2024). "Compared to C-Kit−-LSECs, we secondly clarified that C-Kit+-LSECs had the abilities to reverse steatosis, inflammation and fibrosis of NASH; while upregulate prolipolytic FXR/PPAR-α, downregulate proinflammational TNF-α and profibtotic α-SMA in vitro and in vivo." (PMID 38461242, 2024). "Notably, NAFLD progression from simple steatosis to NASH, with substantial fibrosis, is mediated by inflammatory cytokines, including IL-1β, IL-6, and TNFα, overproduced by resident liver macrophages, i.e., the inflammatory-polarized M1-Kupffer cells." (PMID 37510108, 2023). "In addition, our results showed that XKY treatment significantly diminished hepatic lipid deposition and steatosis accompanied by improved liver function (ATL and AST), lipid profile (TC and TG) and inflammation (TNF-α and IL-6) in db/db mice." (PMID 37202792, 2023). "The accumulation of Th1 cells, dendritic cells, inflammatory monocytes, TNF, IFN-γ, and NO, significantly increased in infected CKO compared with WT mice, could be responsible for the observed non-alcoholic steatosis." (PMID 37908369, 2023). "The adipokines (e.g., leptin, adiponectin, and tumor necrosis factor-α (TNF-α)) derived from the adipose tissue, may contribute to simple steatosis and NASH." (PMID 36838721, 2023). "This proinflammatory cytokine was found to promote steatosis (by stimulating TG synthesis and cholesterol accumulation in the liver), inflammation (by upregulating ICAM-1 and inducing IL-6 and TNFα expression) and fibrosis (by activating HSCs and inducing the production of profibrogenic factors)." (PMID 36768637, 2023). "In vitro experiments on fat-laden human hepatocytes revealed that omentin-1 did not affect steatosis but significantly reduced TNF-α levels, ER stress, and oxidative stress." (PMID 38082368, 2023). "Tumor necrosis factor (TNF) signaling pathway: the expression level of TNF-α was increased in serum samples of NAFLD patients; in contrast, mice with deleted TNF receptors showed attenuated inflammation, steatosis, and fibrosis." (PMID 36639568, 2023).
steatosis (continued). "TNF-α signaling cross-regulates type I IFN signaling by eliciting interferon-stimulated gene expression and increasing inflammation, and IFN-α signaling would, in turn, favor steatosis." (PMID 36159810, 2022). "The presence of TNFα also stimulates SREBP-1c, leading to steatosis." (PMID 36077467, 2022). "HMGB1 kinetics did not correlate with either IL-6 or TNF-α, but with the degree of graft steatosis and postoperative ALT levels." (PMID 36338535, 2022). "Th17/22 cells then release cytokines, including IL-6, IL-17, IL-22, tumor necrosis factor-α (TNF-α), TGF-β and C-C motif chemokine ligand 20 (CCL20), in mouse models of NASH and in patients with steatosis, which further promote tissue inflammation and recruitment of leucocytes." (PMID 34944732, 2021). "Lipid treatment also increased steatosis in healthy (1.89×) and diabetic (2.39×) formulations (p < 0.01), whereas TNF-α, a cytokine secreted by macrophages in adipose tissue, did not drive increased steatosis in monoculture after treatment." (PMID 34162924, 2021). "Steatosis in the WD30 group was confirmed by increased levels of tissue TGs and cholesterol, and inflammation by elevated levels of liver tumor necrosis factor alpha (TNF-α) and interleukin 6 (IL-6) (p < 0.01)." (PMID 34199098, 2021). "Inhibition of SYK could ameliorate the inflammation and steatosis of NAFLD by reducing the activation of macrophages and the production of CCl2, IL-6 and TNF-α." (PMID 34506234, 2021). "We conclude that Kupffer cell-derived TNF is necessary to mediate steatosis in hepatocytes that have not been challenged with a HFD." (PMID 33050035, 2020). "NAC prevented many aspects of NAFLD progression by decreasing the development of oxidative stress and subsequent increases in TNF-α but did not block the development of steatosis." (PMID 33339155, 2020). "NF-κB activation increases the production of downstream inflammatory factors, such as Tumor necrosis factor-α (TNF-α), Interleukin (IL)-1β, and these inflammatory factors have been reported to enable steatosis and liver tissue damage, promoting the occurrence and development of NASH." (PMID 32425782, 2020). "However, supplementation with PIs decreases mRNA levels of the inflammatory cytokines/chemokines, tumor necrosis factor-alpha (TNF-α), and monocyte chemoattractant protein-1 (MCP-1), which are upregulated in steatosis." (PMID 32878279, 2020). "Thus, the activated macrophage increases the expression of inflammatory cytokines, such as tumor necrosis factor (TNF-α) and interleukin-6 (IL-6), which contribute to subsequent steatosis and glucose metabolism disorder." (PMID 32134969, 2020). "The activation of inflammation-mediated cells such as Kupffer cells and hepatic stellate cells (HSCs) plays an important role in the transition from steatosis and NASH via the pro-inflammatory and pro-fibrotic factors, including TNFα, TGF-β, collagen1α1, and αSMA38,39." (PMID 33173107, 2020). "Another female mice model fed with Western diet (WD)-induced NASH increased the expression of genes, including steatosis (SFA, MUFA, MUFA-containing di- and triacylglycerol), inflammation (TNFα), oxidative stress (Ncf2), and fibrosis (Col1A) via lipidomics and transcriptomic approach." (PMID 31795276, 2019). "Although the model did not transpose steatosis, the obese animals (Ob) presented high levels of TNF-α levels, a potent pro-inflammatory cytokine." (PMID 31387231, 2019). "The lack of inflammatory cytokines as steatosis progressed correlated with decreasing activation of NF-κB p65, a transcriptional activator of TNF-α and IL-6." (PMID 31034519, 2019). "Together, these studies with our present findings suggest a new TNFα-IKK-beta-TAp63-CCDC3 pathway that might offer a novel molecular insight into a better understanding of the HFD-induced hepatic inflammation and steatosis." (PMID 28827783, 2017). "(v) Secretory granule numbers do not recover as LB numbers decrease due to reversal of steatosis by TNF alpha." (PMID 29430572, 2017).
steatosis (continued). "Administration of TNF-α antibodies prevented liver necrosis and inflammation, but not steatosis, in rats and knockout mice lacking TNF receptor 1 were protected from the inflammatory responses associated with chronic ethanol administration." (PMID 26891124, 2016). "Compared to the well-established role of TNF-α in alcoholic liver inflammation and cytotoxic, its contribution in ethanol-induced steatosis was not widely characterized." (PMID 26101535, 2015). "The aim of this study was to assess whether two-years treatment with Pirfenidone influences necroinflammation, fibrosis and steatosis, serum levels of TGF-β1, IL-6, TNF-α and CB1 and CB2 gene expression, in patients with chronic hepatitis C (CHC)." (PMID 25064094, 2014). "To further characterize the progressive steatosis and inflammation, we assayed hepatic triglycerides, which were significantly increased in 8 weeks HFD-fed animals, and time dependent increase of mRNA TNF-α content." (PMID 23805238, 2013). "The results demonstrated that in the SS group, pathways including TNF-JNK signaling pathway,IL-1/IL-1R-JNK signaling cascade, and TLR2/4-MAPK signaling axis collectively indicate the role of pro-inflammatory signaling in driving steatosis progression toward fibrosis." (PMID 40918148, 2025). "Therefore, the inflammatory cytokines TNF-α, IL-1β, and IL-18 may combine with CXCL1 to synergistically induce liver injury and steatosis." (PMID 40606614, 2025). "Tyrosol, in addition to improving steatosis, has been shown to ameliorate the inflammatory response triggered by a high-fat diet in mice by preventing up-regulation of JAK1 and STAT3 proteins and therefore of pro-inflammatory cytokines IL-6, tumor necrosis factor-α (TNF-α), and IL-10." (PMID 39452069, 2024). "Interestingly, lipotoxic hepatocytes/HSCs cocultured with C-Kit+-LSECs or the livers of MCD mice receipting of C-Kit+-BMCs (bone marrow cells) showed less steatosis, inflammation and fibrosis, higher expression of prolipolytic FXR and PPAR-α, lower expression of TNF-α and α-SMA." (PMID 38461242, 2024). "Despite the marked steatosis, iVP16LXRα mice did not present an increased hepatic inflammatory signature, as indicated by the halved expression of Tumour Necrosis Factor α (Tnfα), Tumour Growth Factor β (Tgfβ) and Interleukin 6 (Il6) as well as the decreased level of the macrophage marker F4/80." (PMID 38824560, 2024). "However, when comparing steatosis scores between groups, scores for SFC-fed TNFα−/− mice were significantly higher than those of controls, while scores for inflammation were alike between control groups and SFC-fed TNFα−/− mice." (PMID 37683301, 2023). "Macrovesicular steatosis (P = 0.016), donor body mass index (P = 0.013), recipients' pretransplant serum creatinine (P = 0.036), and intrahepatic expression of heme oxygenase 1 (HO1) (P = 0.015) and tumor necrosis factor α (TNF-α) (P = 0.039) were independent predictors of EAD." (PMID 34957150, 2021). "Resveratrol and NAC administration significantly improved liver index (resveratrol only), alanine transaminase, TNF-α, glucose, albumin, malondialdehyde (MDA), GSH, glutathione-S-transferase, total cholesterol, low-density lipoprotein-c, and leptin levels compared with steatosis control values." (PMID 33339155, 2020). "We also found that IL6 and TNFα, two important proinflammatory adipocytokines hugely expressed in the adipose tissue of obese human subjects and patients with IR, were overexpressed in the liver of NAFLD MO women with NASH compared to those with simple steatosis." (PMID 25474087, 2014). "It should be noted, however, that besides their important role as promoters of liver regeneration, TNF‐α and IL‐6 are both showing dichotomous negative effects in the liver, such as promoting cell death, liver toxicity, inflammation, and liver aging, fibrosis, steatosis, respectively." (PMID 40462652, 2025).
steatosis (continued). "Similarly, the prolonged increase of plasma ALT might not merely depend on steatosis but might also rely on high levels of inflammatory molecules TNF-α and LPS, whose effect on liver injury is reported." (PMID 33921866, 2021). "However, in co-cultures or supernatant transfer experiments, we show that tumor necrosis factor (TNF) secretion by Kupffer cells is necessary and sufficient to induce steatosis in hepatocytes, independent of the challenge of hepatocytes with elevated fatty acid levels." (PMID 33050035, 2020). "High concentrations of TNF-α or FFA, previously demonstrated to transform 3D PHH into in vitro models of inflammation and steatosis, respectively, also did not affect ASP+ uptake by spheroids." (PMID 39068198, 2024). "The plasma levels of CX3CL1, TNF, CD40, CSF‐1, and TWEAK were lower in moderate steatosis versus no steatosis." (PMID 35128832, 2022). "Unlike current PCLSs models, which show only steatosis, lipid deposition, and lipotoxicity, human PCLSs under GFIPO after 96 h exhibited markers of liver inflammation, including up-regulated inflammatory genes (TNFα, IL6, and IL1β) and cytokines (TNFα, IL6, IL8), detectable up to 96 h." (PMID 38474754, 2024). "However, TNFα was not significantly different between simple steatosis and NAFLD/NASH patients, suggesting that TNFα may be an acute phase biomarker that is elevated in early liver disease." (PMID 36589452, 2022).